MCL1 (MCL1 apoptosis regulator, BCL2 family member)
Diseases named in the same sentence as MCL1 in open-access papers (continued):
Sharing a sentence is not in itself a finding about the gene and the disease.
cancer (continued). "This differential effect, which is explained by compensatory Mcl-1 function, provides opportunities for patient stratification and combination treatments in the context of cancer chemotherapy." (PMID 27512141, 2016). "MCL1-targeted drugs, such as small molecule inhibitors, have recently been developed to improve the chemotherapy-mediated antitumor effect in human cancer cells." (PMID 27356624, 2016). "It is therefore clear that inhibitors of Mcl-1 hold great promise as a new class of targeting agents and are the current focus of widespread cancer drug development efforts." (PMID 26921175, 2016). "Response variation between different cancer types is also mainly attributed to variable expression, in this case ratio of Bcl-xL/Bak and Mcl-1/Bak." (PMID 27811996, 2016). "The dependence of anti-mitotic drug response on Bcl-xL and Mcl-1 that we derived from the modeling analysis provides a quantitative measure to predict sensitivity of distinct cancer cells to anti-mitotic drug treatment." (PMID 27811996, 2016). "Focal amplification of MCL1 (1q21.2) has been reported as one of the most frequent copy number variation across human cancers and this correlates with addiction to MCL1 in vitro." (PMID 26096930, 2016). "Bcl-2, Bcl-xL, and Mcl-1, antiapoptotic Bcl-2 family proteins, are highly expressed in human cancer through the enhanced binding of transcription factor STAT3 dimer at their promoter regions." (PMID 26194866, 2016). "Despite the confirmed importance of Mcl-1 in several cancers, the role of Mcl-1 in BTC survival has yet to be explored." (PMID 26848531, 2016). "The pro‐survival members of the Bcl‐2 family, including Bcl‐2, Bcl‐xL, and Mcl‐1, are commonly overexpressed in a number of human cancers." (PMID 26696548, 2016). "Bcl family (Bcl-2, Mcl-1), which are known to be crucial for cancer cell survival, are prominent targets for STAT3 and NFκB, and down-regulated as a consequence of STAT3 and NFκB inhibition." (PMID 27539371, 2016). "The MTT results showed that chidamide causes cell growth arrest in a dose- and time-dependent manner in BxPC-3 and PANC-1 cancer cell lines, which is consistent with the inhibitory effects of Mcl-1 knockdown." (PMID 27875574, 2016). "Cardone and co‐workers showed that Cardone compound 9 had high activity in a panel of human derived cancer cell lines, in particular Mcl1‐1780 (EC50=0.3 μm), Bcl2‐1863 (EC50=1.1 μm), NCI‐H929 (EC50=1.6 μm) and SUDHL‐6 (EC50=3.3 μm)." (PMID 26696548, 2016). "Downregulation of Mcl-1 leads to the release of cytochrome c from mitochondria into cytosol, which then leads to caspase activation, whereas overexpression of Mcl-1 protects cancer cells from apoptosis." (PMID 27167344, 2016). "A representative cancer cell line (HeLa) was engineered to overexpress Mcl-1, Bcl-2 or Bcl-xL, and we assayed the activity of the designed inhibitors in each setting." (PMID 27805565, 2016). "The ratio of Bax/Mcl-1 is thus used to determine the status of cancer cells as in apoptosis or antiapoptosis." (PMID 27167344, 2016). "Mcl-1 is frequently upregulated in human cancers, which has been demonstrated to participate in oxidative phosphorylation, in addition to its anti-apoptotic actions as a Bcl-2 family member." (PMID 27875574, 2016). "To further test this assumption, we inspected the proliferation inhibition efficiency of chidamide and Mcl-1 siRNA in pancreatic primary cancer cells." (PMID 27875574, 2016). "Anti-apoptotic proteins such as B-cell lymphoma 2 (Bcl-2), B-cell lymphoma-extra large (Bcl-xl) and Mcl-1 are known to play key roles in cancer cell apoptosis." (PMID 26848531, 2016). "In the present study, we used SP cells from GBC-SD cells as a model of cancer stem-like cells and found that SP cells have higher Mcl-1 expression, consistent with a recent report." (PMID 26848531, 2016).
cancer (continued). "Anti-apoptotic Bcl-2 family proteins such as Bcl-2, Bcl-xL, and Mcl-1 are frequently upregulated in various forms of cancer, promoting tumorigenesis and resistance to chemotherapy." (PMID 26791262, 2016). "Specifically, Mcl-1 is amplified in many cancers including BC and elevated Mcl-1 levels in BC correlate with increased tumor cell survival, growth, and poor prognosis." (PMID 26921175, 2016). "The similar phenomenon has also been reported in previous study (The study shows that Bcl-2/xL inhibitor ABT-263 induces cancer cell apoptosis while upregulates Mcl-1)." (PMID 27449090, 2016). "Anti-apoptotic BCL-2 family proteins, principally BCL-2, BCL-XL and MCL-1, maintain survival of cancer cells by sequestering their pro-apoptotic counterparts." (PMID 26954718, 2016). "In conclusion, our findings show that the novel mechanism of cell death induced by metformin involves TRAIL sensitization and degradation of Mcl-1, important for an understanding of its role in the pathophysiology, diagnosis, and ways to treat cancer." (PMID 27517746, 2016). "While drug-mediated suppression of Mcl-1 levels in cancer cells takes place at multiple instances, commonly this involves reduction of protein stability of Mcl-1." (PMID 26474387, 2015). "Mcl-1, a member of the Bcl-2 family, is highly expressed in various malignant tumors, and plays an important role in inhibiting apoptosis." (PMID 26457704, 2015). "In conclusion, we suggest that Bay 61–3606 is a promising agent for downregulating Mcl-1 expression in cancer cells." (PMID 26720004, 2015). "Before testing the combination effect of TRAIL and the Bcl-2 family inhibitors, we examined the expression of anti-apoptotic Bcl-2 family proteins (Bcl-2, Bcl-xL, and Mcl-1) in nine cancer cell lines." (PMID 26506422, 2015). "We report for the first time that a BH3 mimetic, Sabutoclax, which functions as an inhibitor of all anti-apoptotic Bcl-2 proteins, induced cancer-specific cell death in an Mcl-1-dependent manner through both apoptosis and toxic mitophagy." (PMID 26009874, 2015). "We have previously shown that the Mcl-1 antagonist Sabutoclax alone or in combination with the tumor suppressor mda-7/IL-24 induces cancer-specific cell death in human prostate carcinomas (PC)." (PMID 26009874, 2015). "In cancer, both ERK and AKT signaling confer resistance to apoptosis via upregulation of a panel of anti-apoptotic proteins including MCL1, X-linked inhibitor of apoptosis protein (XIAP) and BCL-xL." (PMID 26517243, 2015). "Previous reports have showed that MMP–2, Bcl–2 and Mcl–1 are direct targets of miR-29a in regulating tumor progression in different cancer cells." (PMID 26441331, 2015). "The anti-apoptotic protein MCL-1 is a key regulator of cancer cell survival and a known resistance factor for small-molecule BCL-2 family inhibitors such as ABT-263 (navitoclax), making it an attractive therapeutic target." (PMID 25590800, 2015). "In our study, we demonstrate a novel mechanism by which GX15-070 elicits its anti-cancer properties beyond the inhibitory effects on Mcl-1." (PMID 26008975, 2015). "All this taken together, CDK9 is an important target kinase that control Mcl-1 stability and turnover in cancer cells." (PMID 26720004, 2015). "A simultaneous elevation of Mcl-1 in naïve HER2-positive cancer cells antagonized the pro-apoptotic effect of Bim." (PMID 26405162, 2015). "It is also noteworthy that LA induced from 48 h, a complete down expression of Mcl-1, an anti-apoptotic protein often up-regulated in cancer cells." (PMID 26063499, 2015). "The BH3 mimetic Sabutoclax, which significantly targets Mcl-1 in addition to the other anti-apoptotic Bcl-2 proteins, induced cancer-specific cell death in OSCC alone or in combination with Celecoxib." (PMID 26009874, 2015).
cancer (continued). "This pathway is all the more interesting that it is known to regulate Mcl-1 translation and is targeted in this way to sensitize several types of cancer justifying the development of pharmacological PI3K/AKT/mTOR inhibitors." (PMID 25627260, 2015). "It is interesting to note that ARNT is located at chromosome 1q21.3, a region that is amplified in several cancers with MCL-1 gene amplification and inhibits cancer cell apoptosis." (PMID 25839165, 2015). "Our study opens avenues for the investigation of key signaling events and the potential role of Mcl-1 as an indicator of anti-cancer activities of these compounds beyond apoptosis." (PMID 26068790, 2015). "Cancer cells modulate Mcl-1 by exploiting a number of redundant pathways regulating at transcriptional, translational, and post-translational levels." (PMID 26219338, 2015). "Mcl-1 modulation ubiquitously occurs in different cancer cell models, independently of origin and characteristics, following treatment with CGs." (PMID 26068790, 2015). "The Bcl-2 family of proteins, especially Bcl-xL and Mcl-1, were found to be elevated in CaP and higher expression correlated with therapy resistance, thus representing a potential target for primary cancer treatment and combinatorial treatment with CRCAs." (PMID 25926554, 2015). "MCL1 was reported to be amplified in 10.9 % of tumor samples analyzed, spanning multiple cancer subtypes." (PMID 26134786, 2015). "MCL-1 is one of the most highly amplified genes in a broad range of human cancers and its expression rapidly changed in responds to cellular stresses." (PMID 26474278, 2015). "Collectively, these results indicate that expression of NS4B in human hepatocytes induces cancer-related NF-κB target genes including C-myc, Mcl-1, Cyclin D1 and MMP-9 via EOR-Ca2+-ROS-NF-κB pathway." (PMID 25875501, 2015). "The data suggest that Sabutoclax-induced cancer-specific reduction in cell viability occurs in a Mcl-1-dependent manner." (PMID 26009874, 2015). "TTP negatively regulates cell growth in several cancer cell types by inhibiting the stability of many mRNA implicated in cell cycle (c-Myc, cyclin D1), inflammation (TNFα, COX-2), apoptosis (Bcl-2, Mcl-1), and angiogenesis (VEGF)." (PMID 26343742, 2015). "We observed that both metformin and aspirin significantly inhibited the activity of STAT3, and STAT3 was previously showed to regulate Mcl-1 and Bcl-2 in various cancer cell lines." (PMID 26056043, 2015). "ARNT was amplified in almost all cancer cell lines, and its amplification was correlated with MCL-1 amplification (r2 = 0.9184)." (PMID 25839165, 2015). "Previous reports showed that high Bcl-2 or low Mcl-1 expression correlate with in vitro sensitivity of several cancer cell lines to ABT-737." (PMID 26392332, 2015). "It has been reported that high expression of Mcl-1 significantly reduced ABT-737 cytotoxicity in several cancers, including ALL." (PMID 26392332, 2015). "Extended mitotic arrest following treatment of cancer cells with microtubule-targeting agents led to phosphorylation of Bcl-2 and Bcl-x followed by Noxa-dependent Mcl-1 degradation." (PMID 26405162, 2015). "We found that Sabutoclax induced cancer-specific cell death in OSCC in a Mcl-1-dependent manner, which was attributed to both Bak-induced apoptosis and Bnip3-mediated mitophagy." (PMID 26009874, 2015). "In our study, we found that the depletion or the inactivation of CUL4B resulted in the accumulation of HUWE1, and thereby accelerated the degradation of its substrate, MCL-1, rendering cancer cells sensitive to DNA damage agents." (PMID 25883150, 2015). "In this study, we report for the first time that pharmacological inhibition of Mcl-1 using Sabutoclax induced cancer-specific cell death in OSCC both in vitro and in vivo." (PMID 26009874, 2015). "MCL-1 is an important member of antiapoptotic BCL-2 family proteins, which is overexpressed in many human cancer cells associated with poor prognosis." (PMID 26526790, 2015).
cancer (continued). "Mcl-1 has recently been recognized as a therapeutic target in cancer, and a related therapy has been tested in preclinical models." (PMID 25890498, 2015). "As a member of anti-apoptotic proteins in BCL-2 family, MCL1 is overexpressed in many kinds of human cancers." (PMID 25685062, 2015). "The anti-apoptotic B-cell lymphoma 2 (BCL-2) family proteins, including BCL-2, BCL-XL, and MCL-1 have been characterized as key survival factors in multiple cancer types." (PMID 26134786, 2015). "Mcl-1 is frequently overexpressed in a variety of human cancers thereby providing protection to the tumor cells from apoptosis." (PMID 26497853, 2015). "When Bim is expressed at relative high basal levels, the cancer cells have often developed a mechanism (e.g., concomitant Mcl-1 or Bcl-2 upregulation) that antagonizes the pro-apoptotic function of Bim." (PMID 26405162, 2015). "High protein expression levels and somatic copy-number amplifications of the MCL1 gene have been found in several cancer types." (PMID 25749045, 2015). "Mcl-1 contributes to oncogenesis by both promoting apoptotic resistance and supporting high-rate proliferation of cancer cells, which makes it a critical molecule in cancer initiation and progression." (PMID 26056043, 2015). "It has recently been shown that a novel CDK9 inhibitor inhibits RNA pol II phosphorylation and Mcl-1 transcription, thus showing strong anti-cancer therapeutic activity." (PMID 26720004, 2015). "Using next-generation sequencing, MCL1 has been identified as the most amplified gene in a screen of 3,000 individual cancers, highlighting its importance for cancer and suggesting a unique function of MCL1 amongst the antiapoptotic BCL2-proteins." (PMID 26556430, 2014). "Upregulation of anti-apoptotic proteins, including Bcl-2 and Mcl-1, or downregulation of pro-apoptotic Bax and Bak has been associated with resistance to TRAIL and recurrence of cancer." (PMID 24765133, 2014). "Approaches abrogating the Mcl-1’s anti-aptototic function either by reducing its abundance or by inactivating its functional BH3-binding groove show great promise for the cancer treatment." (PMID 24789074, 2014). "Previous studies linked the anticancer activity of NCTD to downregulation of Bcl-2, Bcl-xL and Mcl-1 since it was found that NCTD reduced the level of these antiapoptotic Bcl-2 family proteins in various cancer cells." (PMID 25022352, 2014). "Mcl-1 is an anti-apoptotic protein of the Bcl-2 family that is essential for the survival of multiple cell lineages and that is highly amplified in human cancer." (PMID 24814761, 2014). "Within this family, several anti-apoptotic members, such as B-cell lymphoma-extra large (Bcl-Xl) and myeloid cell leukemia 1 (Mcl-1), are overexpressed in cancer." (PMID 25478322, 2014). "MCL-1 plays critical roles in cancer cell survival and drug resistance against chemotherapy and become a promising therapeutic target for MM treatment." (PMID 25422792, 2014). "In hematological malignancies several compounds have already been demonstrated to have the ability to sensitize cancer cells to ABT-737-induced cell death either through Mcl-1 down-regulation or up-regulation of the endogenous Mcl-1 inhibitor Noxa." (PMID 25008202, 2014). "Myeloid cell leukemia-1 (Mcl-1), an anti-apoptotic member of the Bcl-2 family, has a pivotal role in protecting cells against apoptosis and is overexpressed in various human cancers." (PMID 24348795, 2014). "Knockdown of Mcl-1 can sensitize cancer cells to apoptosis induced by different stimuli, such as serum starvation or chemotherapeutic drugs." (PMID 25337143, 2014). "We also found that TRAF6 stabilized MCL-1 in mouse fibroblasts and in several cancer cell lines including HeLa and MCF-7." (PMID 25340740, 2014). "Since then, many studies have identified MCL1 as highly amplified in cancer, emphasizing its importance for carcinogenesis." (PMID 26556430, 2014).
cancer (continued). "Although ABT-737, a small-molecule Bcl-2/Bcl-xL inhibitor, has recently emerged as a novel cancer therapeutic agent, ABT-737-induced apoptosis is often blocked in several types of cancer cells with elevated expression of Mcl-1." (PMID 25375379, 2014). "Increased MCL1 levels in cancer cells can result from elevated transcription or translation and decelerated degradation." (PMID 24564888, 2014). "It is known that Mcl-1 is an important anti-apoptotic protein, which is now becoming a quite important target for cancer therapy." (PMID 24779770, 2014). "In fact, CDKI-71 induces apoptosis by downregulating the anti-apoptotic factor Mcl-1 in various cancer cell lines with minimal effects in normal fibroblasts and B and T-cells." (PMID 24576043, 2014). "As a B-cell lymphoma-2 (BCL-2) family member, myeloid cell leukemia-1 (MCL-1) plays critical roles in promoting the survival of MM cells as well as a wide range of other cancer cells due to its anti-apoptosis activities." (PMID 25422792, 2014). "One of the major mechanisms by which cancer cells evade apoptosis is by over expressing Bcl-xL, Bcl-2 and/or Mcl-1 contributing not only to tumorigenesis but also to tumor resistance to chemotherapy." (PMID 25076060, 2014). "Others reported that antiapoptotic Bcl-2 proteins, e.g. Mcl-1, were rapidly and completely degraded in cancer cells treated with Obatoclax." (PMID 25192188, 2014). "This is consistent with emerging findings showing that Mcl-1 degradation through this pathway is impaired in many different types of cancer." (PMID 24814761, 2014). "Although MCL-1 is a highly labile protein, it is commonly overexpressed in cancers and contributes to cell survival and drug resistance although the precise mechanisms have yet to be completely elucidated." (PMID 25340740, 2014). "In many cancers, Mcl-1 appears to be essential for cancer cells to overcome oncogenic stress-induced apoptosis." (PMID 24814761, 2014). "It has showed selective targeting MCL-1 or its upstream modulatory molecules by RNA interference induced cancer cell death." (PMID 25422792, 2014). "In this study, we show that cafestol acts as a potent enhancer of ABT-737-induced apoptosis in cancer cells, which have Mcl-1-mediated resistance to ABT-737." (PMID 25375379, 2014). "Mcl-1 overexpression also appears to be a key factor in the resistance of various cancer types to conventional treatments, including radiation and chemotherapy." (PMID 25409302, 2014). "Our current results suggest that the abilities of JY-1-106 to bind both Mcl-1 and Bcl-xL contribute to Bax activation in these cancer cells." (PMID 23680104, 2013). "In recent years, it is increasingly being realized that over-expression of Mcl-1 contributes to cancer progression and confers resistance to apoptosis." (PMID 23593315, 2013). "Overexpression of anti-apoptotic proteins such as Bcl-xL and Mcl-1 have been reported to greatly contribute to cell survival and drug resistance in various human cancers." (PMID 24103422, 2013). "In recent years, it has been learnt that the effectiveness of BAD BH3-mimetics are dependent on the Mcl-1 expression and studies suggest that cancer cells can quickly acquire resistance to ABT-737 by up-regulation of Mcl-1." (PMID 24223823, 2013). "Numerous reports indicate that Mcl-1 overexpression in a variety of cancers can mediate resistance to ABT-737." (PMID 24058878, 2013). "Mcl-1 reduction significantly enhances the sensitivity of cancer cells to ABT-737 and other chemotherapeutics." (PMID 23680104, 2013). "This would expand the pool of free pro-apoptotic effectors and, thus, induce apoptosis in cancer cells in which overexpressed Bcl-2, Bcl-xL, or Mcl-1 provide survival cues." (PMID 23680104, 2013).